U8 (U8 small nucleolar RNA )
Synonyms: LOC124900518
Gene: Small nucleolar RNA gene on chromosome 2 (185,661,774 to 185,661,906, forward strand). Ensembl gene ENSG00000212581.
Gene Ontology:
Biological process: RNA processing
Cellular component: nucleolus
Homologues: Orthologues: chimpanzee U8 (100% identical), macaque U8 (94% identical), pig U8 (58% identical). Paralogues in human: U8 (80% identical), U8 (79% identical), U8 (78% identical), U8 (77% identical), U8 (75% identical), U8 (74% identical), U8 (73% identical), U8 (71% identical), U8 (70% identical), U8 (69% identical), U8 (68% identical), U8 (59% identical), and 1 more.